UBE2T (ubiquitin conjugating enzyme E2 T)
Diseases named in the same sentence as UBE2T in open-access papers (continued):
Sharing a sentence is not in itself a finding about the gene and the disease.
cancer (continued). "Such insights may pave the way for novel strategies in cancer diagnosis and treatment, enhancing our understanding of UBE2T’s role in cancer biology and supporting the development of innovative therapeutic approaches." (PMID 39791716, 2024). "In recent years, high UBE2T expression in various cancers has garnered significant attention." (PMID 39791716, 2024). "Additionally, microRNAs have been shown to target UBE2T across different cancers, inhibiting its oncogenic effects and offering another potential strategy for therapeutic intervention." (PMID 39791716, 2024). "Our findings demonstrated that UBE2T could be a therapeutic target, as well as a predictor of survival and immunotherapy in cancer treatment." (PMID 36357897, 2022). "In addition, UBE2T-mediated ubiquitination regulates several cancer-relevant pathways, including the ubiquitination of AKT, which activates the AKT/β-catenin pathway, and the ubiquitination of β-catenin, which induces its nuclear translocation." (PMID 36338541, 2022). "ANLN and UBE2T are widely expressed in various cancer tissues." (PMID 35578283, 2022). "UBE2T has been characterized as an oncogene in many types of cancer, including HCC." (PMID 34614271, 2022). "UBE2T expression has also been considered to serve as an early biomarker for cancer prognosis." (PMID 36338541, 2022). "Overall, UBE2T expression was significantly upregulated in various cancers." (PMID 36357897, 2022). "Pan-cancer tests have also shown that UBE2T is critical for TME." (PMID 36245987, 2022). "Ubiquitin-conjugating enzyme E2T (UBE2T) acts as an oncogene in various types of cancer." (PMID 34461934, 2021). "Meanwhile, UBE2T overexpression has also been found in a variety of cancers." (PMID 34838005, 2021). "UBE2T acts as an oncogene and is observed to be upregulated in multiple types of cancers." (PMID 34900723, 2021). "The E2 ligase UBE2T (FANCT) has not been linked with chemoresistance in ovarian or other cancer types and is a recently categorised FA protein." (PMID 36046263, 2020). "UBE2T was a widely reported oncogene in many types of cancers." (PMID 33087136, 2020). "Previous studies demonstrated that UBE2T over-expression promotes cancer development." (PMID 32491994, 2020). "Importantly, the UBE2T gene, located at 1q32.1, has been reported to be overexpressed in several malignant tumors, such as bladder cancer, hepatocellular carcinoma, myeloma, and renal cell carcinoma." (PMID 32025379, 2020). "Notably, UBE2T locates at 1q32.1, and the gain of 1q is frequently observed in a variety of cancers." (PMID 27729585, 2016). "The fact that UBE2T locates at 1q32.1 and the gain of 1q can been observed in most cancers, which may result in the increased expression of UBE2T, leads further support to the possibility of UBE2T as an oncogene." (PMID 26308072, 2015). "Thus, BA's transcriptional suppression of UBE2T through ERK inhibition may represent a balanced way to exploit FA dependency in cancer cells." (PMID 41486508, 2026). "A deeper understanding of UBE2T’s role in this pathway could lead to new targeted cancer therapies." (PMID 39791716, 2024). "Moreover, UBE2T could activate the Wnt signaling pathway to enhance the stemness of HCC cancer stem cells." (PMID 36357897, 2022). "Besides, we further assessed the prognostic value of UBE2T for pan-cancer." (PMID 36245987, 2022). "Collectively, these results suggest that UBE2T may be a therapeutic target for cancer." (PMID 34257599, 2021). "Numerous studies have demonstrated that miRNAs inhibit cancer cell proliferation, invasion, migration, and EMT by negatively regulating UBE2T across various cancers." (PMID 39791716, 2024).
cancer (continued). "UBE2T is also involved in activating oncogenic signaling pathways, such as the mTOR and TNFA signaling pathways, which are known to modulate cancer growth and progression." (PMID 36338541, 2022). "Many studies have shown that UBE2T affects AKT/GSK3‐β, as well as Wnt/β‐catenin pathway in many types of cancer including HCC." (PMID 34614271, 2022). "To test the effects of UBE2T, TK1, CXCL12, and KPNA2 on cancer cell invasion, we knocked down these genes in murine CAFs via siRNAs." (PMID 35884546, 2022). "Another study shows that miR-1305 targets UBE2T to inhibit the AKT pathway, thereby suppressing the self-renewal and tumorigenicity of live cancer stem cells." (PMID 33934686, 2021). "The profile of expression of UBA1, UBE2C, UBE2T, UBE2O, and CCNF in BRCA seemed to support their involvement in cancer initiation and progression." (PMID 34201347, 2021). "Alongside FA-mediated drug resistance are observations that FANCA and FANCT/UBE2T correlate with poor prognosis and survival of cancer patients." (PMID 32190289, 2020). "A deeper understanding of UBE2T’s role in the PI3K-AKT pathway could yield novel insights for developing anti-cancer strategies, overcoming drug resistance, and improving cancer immunotherapy efficacy." (PMID 39791716, 2024). "The oncogene protein ubiquitin-conjugating enzyme E2T (UBE2T) is a ubiquitin-conjugating enzyme (E2) which was widely reported to be upregulated and promotes tumorigenesis, proliferation, and metastasis in various cancers in an E2 activity-dependent manner." (PMID 35169125, 2022). "Preferential expression of UBE2T in cancerous tissues to adjacent non-cancerous tissue has been found in a broad spectrum of cancers." (PMID 34257599, 2021). "Although, FAM64A and UBE2T were not validated both in independent dataset and qRT-PCR, they still play important roles in cancer." (PMID 33313822, 2021). "Data from Oncomine and GEPIA datasets showed that the mRNA level of UBE2T was significantly higher in GC tissues, Moreover, GEPIA database showed that the mRNA level of UBE2T was also upregulated in 24 additional cancer types." (PMID 33323973, 2021). "Therefore, the important discovery that UBE2T is deSUMOylated and activated by SENP1 suggests an arresting novel mechanism to promote UBE2T SUMOylation in human cancer." (PMID 31969492, 2020). "We identified a novel UBE2T downstream substrate, namely GRP78, a regulator that could promote tumorigenesis, metastasis and drug resistance in cancers." (PMID 32491994, 2020). "Aberrant Wnt signaling which is triggered by UBE2T overexpression is a feature of advanced HCC characterized by the activation of other main oncogenic pathways such as AKT/mTOR, MAPK/ERK, and TGF‐β, which are affected differently in 2D and 3D conditions in many cancers including HCC." (PMID 34614271, 2022). "However, the implications of UBE2T in many other types of cancers are lacking." (PMID 36357897, 2022). "However, to the best of our knowledge, no targeted agents against UBE2T, UBE2C, BIRC5, or USP9X, either approved or in development, can be found in The Drug Gene Interaction Database or Genomics of Drug Sensitivity in Cancer database, while the only USP7 inhibitor, P22077, has not been tested in BC." (PMID 33671201, 2021).
hematologic neoplasms (1 paper, 2025).
infection (1 paper, 2017). The state of being infected such as from the introduction of a foreign agent such as serum, vaccine, antigenic substance or organism. "siRNA infection dramatically decreased UBE2T gene expression in SGC-7901, BGC-823, and AGS cells (P < 0.01)." (PMID 28427240, 2017). "Western blots revealed that UBE2T protein expression also dramatically decreased in SGC-7901, BGC-823, and AGS cells after siRNA infection." (PMID 28427240, 2017).
UBE2T also shares sentences with these, for which no sentence is quoted: invasive breast carcinoma (3 papers); adenocarcinoma (2); breast invasive ductal carcinoma (2); skin cutaneous melanoma (2); adrenocortical carcinoma (1); autosomal recessive disease (1); bone marrow failure syndrome (1); cardiac diseases (1); cervical tumor (1); Cirrhosis (1); clear cell renal cell carcinoma (1); colon cancer (1); dengue (1); dyskeratosis congenita (1); epithelial ovarian cancer (1); esophageal adenocarcinoma (1); Fanconi anemia complementation group D2 (1); genetic disorder (1); heart failure (1); Hepatitis (1); Hereditary breast cancer (1); influenza (1); invasive carcinoma (1); kidney cancer (1); kidney chromophobe (1); lentivirus infection (1); lobular carcinoma (1); lung squamous cell carcinoma (1); lymphoma (1); ovarian serous cystadenocarcinoma (1).
A further 10 diseases each share a sentence with UBE2T in 1 paper.